PAX5 (paired box 5)
Diseases named in the same sentence as PAX5 in open-access papers (continued):
Sharing a sentence is not in itself a finding about the gene and the disease.
neuroblastoma (9 papers, 2004 to 2024). Neuroblastoma (NB) is the most common solid, extracranial childhood tumor. "Similar to CRPC, Pax5 expression has been detected in neuroendocrine lung cancer as well as N-type neuroblastoma cells and reported to be associated with aggressive nature of cancers." (PMID 38168280, 2023). "Some of these transcription factor complexes have been implicated in neuroblastoma tumorigenesis, including E2F, PAX5, and RFX1." (PMID 27732954, 2016). "This study also demonstrates that recombinant expression of PAX5 in benign neuroblastoma cell models resulted in more invasive cancer phenotypes." (PMID 36077495, 2022). "Other reports have also shown a role for PAX5 in oncogenic or pro-aggressive features in astrocytoma, lung cancer, cervical carcinoma, bladder cancer, oral carcinoma, neuroblastoma, and medulloblastoma." (PMID 36077495, 2022). "PAX5 is expressed in aggressive N-type neuroblastoma cell lines, and downregulation of this transcription factor significantly reduced their proliferation rate and tumorigenic phenotype." (PMID 34570823, 2021). "PAX5 has been observed as overexpressed in other neuroendocrine tumours, overexpressed in neuroblastoma, and shown to positively regulate c-Met transcription in small cell lung cancer." (PMID 29757368, 2018). "In contrast to the stable expression of Pax-5 there appeared to be large differences in E-protein expression in the neuroblastoma cell lines investigated." (PMID 15544702, 2004). "The finding that neuroblastoma cells expressed Pax-5 was somewhat surprising even though this factor has been shown to be involved in midbrain development." (PMID 15544702, 2004). "Since the binding activity of several transcriptions factors such as E-proteins and EBF appear to be modulated during the induced differentiation of neuroblastoma cells we wanted to investigate if this was the case also for Pax-5." (PMID 15544702, 2004). "We can assume that the oncogenic effects of PAX5 may be associated with its negative regulation of expression of GRHL1 and GRHL3, since GRHL1 has been shown to be a tumor suppressor in neuroblastoma, whereas GRHL3 is a tumor suppressor in head and neck SCC." (PMID 34570823, 2021). "Pax-5 protein could also be detected in the neuroblastoma cell lines IMR-32, KCN-69n and LA-N-1." (PMID 15544702, 2004). "Thus, several neuroblastoma cell lines express both EBF proteins and Pax-5, two genes known to induce expression of the mb-1 and CD19 genes in pre-B cells, but neuroblastoma cells nevertheless fail to express these two target genes." (PMID 15544702, 2004). "While the control antibody did not affect formation of the complex the Pax-5 antibody resulted in a reduced DNA binding and also the appearance of a weak super-shifted band using either pre-B (Data not shown) or neuroblastoma nuclear extracts." (PMID 15544702, 2004). "It is currently not clear whether a link between Pax-5 and Notch1 expression is at hand in neuronal cells, but it is noteworthy that neuroblastoma cells express relatively high levels of Pax-5." (PMID 15544702, 2004).
prostate carcinoma (9 papers, 2019 to 2024). A carcinoma that arises from epithelial cells of the prostate gland. "Overall, the current work emphasizes the role of Pax5 transcriptional signature as a crucial element in neuronal gene expression linked to therapy-resistant prostate cancer." (PMID 38168280, 2023). "DPP4 and PAX5 are significantly associated with the prognosis of prostate cancer patients." (PMID 33407865, 2021). "Similar to LuCaP models, we also analyzed Pax5 expression in the TMA derived from the metastatic PCa patients [Prostate Cancer Biorepository Network (PCBN]." (PMID 38168280, 2023). "In prostate cancer, PAX5 promotes the expression of IDH1-AS1 transcriptionally, regulating cell proliferation and apoptosis." (PMID 36064939, 2022). "Upregulation of PAX5 was found to induce the forkhead box P4 axis and promote tumorigenesis in prostate cancer." (PMID 35008387, 2022). "As a comparison we investigated PAX gene expression in the melanoma cell line UACC62 which had only PAX8 expression (0.04-fold), and the prostate cancer cell line PC-3 which expressed PAX6 at 5-fold and PAX5 and PAX8 at the same level as housekeepers (1-fold)." (PMID 34722257, 2021). "Paired box 5 (PAX5) is capable of triggering FOXP4-AS1 expression that in turn, functions as ceRNA for miRNA-3184-5p, leading to post-transcriptional regulation of FOXP4 and increasing its expression in favor of prostate cancer progression." (PMID 35773731, 2022). "Finally, we validated Pax5 expression in tissue microarrays (TMAs) derived from prostate cancer patient derived xenografts (PDX) (LuCaP series) and from metastatic CRPC (mCRPC) tissues obtained from Prostate Cancer Biorepository Network (PCBN)." (PMID 38168280, 2023).
T-cell lymphomas (9 papers, 2014 to 2026). "At immunohistochemistry, the prevalent cell immunoreactivity for B cell markers (CD20, CD79a, and PAX5) or for the T cell marker (CD3) was considered diagnostic for B cell (BCL) and T cell lymphoma (TCL), respectively." (PMID 36157173, 2022). "As ectopic Pax5 expression in the T‐lymphoid lineage leads to the development of an aggressive T cell lymphoma, we used the Cd79a‐Cre line to convert the Ikzf1neo to the Ikzf1Pax5 allele only at the onset of B cell development." (PMID 35156727, 2022). "The peripheral T-cell lymphomas showed a diffuse growth pattern, and neoplastic cells were diffusely immunoreactive for CD3 but immunonegative for PAX5." (PMID 37104402, 2023). "In contrast to CHL, ALCL and other T cell lymphomas lack PAX5 expression, and the complete lack of PAX5 in a putative case of CHL should prompt more extensive phenotyping, including ALK protein and cytotoxic markers." (PMID 35159009, 2022). "Although, Pax-5 completely arrests T-cell development, its expression has been reported in some mature T-cell lymphomas but not in T-cell LBL." (PMID 24950962, 2014).
B-cell acute lymphoblastic leukaemia (8 papers, 2016 to 2025). "Recent reports revealed that pre-leukemic HSPCs carrying an ETV6-RUNX1 fusion gene or having Pax5 haploinsufficiency evolved to precursor B cell acute lymphocytic leukemia upon activation of the pro-inflammatory pathways." (PMID 32821971, 2020). "Current study is designed to evaluate the role of FLT3 and PAX5 genes in B-cell lymphoblastic leukemia." (PMID 31565544, 2019). "Previous studies revealed that as a B-lymphoid transcription factor, PAX5 was downregulated in over 80% of pre-B cell acute lymphoblastic leukaemia (ALL), and its downregulation in lymphoid neoplasms was associated with promoter hypermethylation and poor clinical outcomes." (PMID 33397394, 2021). "The positive enrichment for genes with promoters containing Pax4 motifs could be related to the observations that the paralogue Pax5 interacts with Elk3, and aberrant Pax5-Elk3 fusion proteins are found in childhood precursor B-cell acute lymphoblastic leukaemia." (PMID 27427904, 2016). "Recently, NOTCH3, PAX5, CBFB, and particularly ACD were shown to drive the activated RAS pathway and monosomy 7 to B-acute lymphoblastic leukemia." (PMID 36980962, 2023).
gastric cancer (8 papers, 2014 to 2024). A primary or metastatic malignant neoplasm involving the stomach. "For instance, PAX5 is a functional tumor suppressor in gastric cancer and PAX5 promoter methylation is related to the survival of gastric cancer patients." (PMID 38221932, 2024). "It has been shown that there was a significant correlation between PAX5 methylation and survival in a sample of Chinese gastric cancer patients." (PMID 33883026, 2021). "Methylation status of PAX5 was assessed in blood samples of Iranian gastric cancer patients compared with healthy blood samples." (PMID 33883026, 2021). "In gastric cancer, PAX5 functioned as a tumour suppressor via promoter hypermethylation and suppressed cell proliferation and apoptosis." (PMID 33397394, 2021). "In previous study, PAX5 promoter methylation was found in gastric cancer (GC) cells and tissues." (PMID 25277182, 2014). "Furthermore, paired box 5 (PAX5) is a novel functional tumor suppressor in gastric carcinogenesis, and detection of methylated PAX5 can be utilized as an independent prognostic factor in gastric cancer." (PMID 25788990, 2015). "In gastric cancer, methylation status of one or more individual CpG sites in genes DACT1, PAX5, and RUNX3 promoter region was also applicable for prognosis." (PMID 29610526, 2018).
chronic lymphocytic leukemia (7 papers, 2016 to 2025). "Several objects of PAX5 overlap with the PAX5 enhancer described as recurrently mutated in chronic lymphocytic leukemia, suggesting that HbP may cause enhancer hypermutation." (PMID 33953289, 2021). "J. Ott and colleagues identified a SE-based CRC in chronic lymphocytic leukemia (CLL) involving PAX5, FOXP1, RARA, ETS1, IRF2, and IRF8, highlighting PAX5's dominant role." (PMID 40083704, 2025). "Similarly, in a chronic lymphocytic leukemia (CLL) patient, treatment with PI3Kδ inhibitor led to a switch from lymphocytic leukemia to Langerhans cell histiocytosis (LCH) with acquired BRAF V600E and STK11 mutations, and loss of expression of B-cell lineage markers such as PAX-5." (PMID 34298815, 2021).
acute leukemia (6 papers, 2015 to 2025). A clonal (malignant) hematopoietic disorder with an acute onset, affecting the bone marrow and the peripheral blood. "For example, reduced expression of human PAX5 during the development of early lymphoid progenitors committed to B lineage has been associated with biphenotypic cells and acute leukemia." (PMID 29492206, 2018). "The finding of the downregulation of NF-κB, PAX5, and Ikaros 55 and 75 kD under the influence of SMCAF in certain acute leukemia cell lines is of significance." (PMID 39408690, 2024).
anaplastic large cell lymphoma (6 papers, 2016 to 2025). Anaplastic large cell lymphoma (ALCL) is a rare and aggressive peripheral T-cell non-Hodgkin lymphoma, belonging to the group of CD30-positive lymphoproliferative disorders, which affects lymph nodes and extranodal sites. "However, it is of note that aberrant expression of PAX5 has been reported in ALK-negative anaplastic large cell lymphoma (ALCL), secondary to extra copies of the PAX5 gene." (PMID 35159009, 2022). "Case LYWS-1418 from J Coviello was a case of CD30+ large cell lymphoma with features of ALK-negative anaplastic large cell lymphoma (ALCL) and possible PAX5 expression in rare CD30+ tumor cells, raising the differential diagnosis of CHL with expression of T-cell markers." (PMID 37646869, 2023).
lymphoid neoplasm (6 papers, 2016 to 2024). A neoplasm composed of a lymphocytic cell population which is usually malignant (clonal) by molecular genetic and/or immunophenotypic analysis. "PAX5 haploinsufficiency occurred frequently in lymphocytic neoplasm and plays an important role in lymphocytic tumorigenesis." (PMID 28316978, 2017). "So, PAX5 haploinsufficiency plays an important role in lymphocytic neoplasm." (PMID 28316978, 2017). "Although PAX5 is considered a better marker than CD19 in mature lymphoid neoplasms, it should be noted that its expression is not entirely specific." (PMID 32604737, 2020).
mantle cell lymphoma (6 papers, 2017 to 2025). Mantle cell lymphoma is a rare form of malignant non-Hodgkin lymphoma affecting B lymphocytes in the lymph nodes in a region called the ``mantle zone''. "Through screening for molecular vulnerabilities of mantle cell lymphoma (MCL), we identified a set of transcription factors (TFs) including FOXO1, EBF1, PAX5, and IRF4 that are essential for MCL propagation." (PMID 36282572, 2022).
astrocytoma (5 papers, 2004 to 2022). "For example, some researchers demonstrated that Pax-5 expression levels correlate with more aggressive forms of astrocytomas, neuroendocrine tumors, and pulmonary carcinomas." (PMID 28076843, 2017). "Elevated expression levels of Pax-5 has been detected in two other tumors of neuronal origin, medulloblastoma and astrocytoma and in vitro data as well as observed translocations in human B lineage tumors indicate that Pax-5 have oncogenic properties." (PMID 15544702, 2004). "The expression of Paired box 5 (PAX5) was increased in a range of astrocytoma." (PMID 36064939, 2022).
myeloid leukemia (5 papers, 2017 to 2020). A clonal proliferation of myeloid cells and their precursors in the bone marrow, peripheral blood, and spleen. "In addition, Hoxa9 and Mzf1 involved in development of myeloid leukemia were up-regulated, while genes associated with differentiation, including Pax5 and Sox4, were down-regulated in both DKI and Dnmt3aR878H/+ groups." (PMID 31703632, 2019). "Notably, the Kmt2a-Mllt1 myeloid leukemia can be established in the Pax5 +/− background with similar dynamics as in the Pax5 +/+ background confirming that a reduced Pax5 gene dosage does not influence the leukemogenic activity of Kmt2a-Mllt1." (PMID 33134860, 2020).
Obesity (5 papers, 2019 to 2023). Accumulation of substantial excess body fat. "Paired box 5 (PAX5) genes were also associated with elevated BP in French Canadian adolescents with obesity (12–18 years old)." (PMID 37324619, 2023). "We found four strains with lower metabolic rate that might predict obesity susceptibility, Pax5+/-, Chst8-/-, Tfap2b+/-, and Pald1-/-." (PMID 32356724, 2020). "Strains with lower metabolic rate which might contribute to development of obesity include Chst8, Pax5, Pald1, and Tfap2b." (PMID 32356724, 2020). "Due to high species conservation, the identified genes related to human or mice obesity traits may hold importance for adipose deposition in chickens, such as ELOVL7, IL6ST, IQGAP2, PAX5 and CKMT2." (PMID 34058970, 2021).
ovarian carcinoma (5 papers, 2016 to 2023). A malignant neoplasm originating from the surface ovarian epithelium. "It was suggested that PAX2 and PAX5 play tumor suppressor roles in ovarian cancer and leukemia, while conversely, PAX3, PAX7, and PAX6 were reported to be oncogenic in embryonal rhabdomyosarcomas and retinoblastoma." (PMID 31235851, 2019). "Interestingly, PAX5 promoter hypermethylation has been observed in ovarian cancer." (PMID 32260415, 2020).
pancreatic cancer (5 papers, 2021 to 2026). "Besides, B cells could produce IL-35 in tumor regulates the unique transcriptional state of B cells and antagonizes plasma cell differentiation by stably expressing B-cell lineage-defining transcription factors Pax5 and Bcl6, to enable pancreatic tumor growth." (PMID 37505298, 2024).
colorectal cancer (4 papers, 2021 to 2024). A primary or metastatic malignant neoplasm that affects the colon or rectum. "PAX5 methylation was observed in 26 (87%) patients with colorectal cancers and in 17 (57%) controls." (PMID 35390065, 2022). "PAX5 methylation as a biomarker to discriminate patients with colorectal cancer from healthy controls had a sensitivity of 87%, but a specificity of only 43%." (PMID 35390065, 2022). "We used RT-qPCR to determine the relative expression levels of four paired box (PAX) genes which are most likely to encode binding targets for EG1 in colorectal carcinoma cells (PAX2, PAX5, PAX6, PAX8)." (PMID 34722257, 2021). "In addition, chromatin immunoprecipitation (ChIP) assays and promoter luciferase reporter assays revealed that PAX5 could activate the transcription of SNHG25 in colorectal cancer cells." (PMID 37751586, 2023).
glioblastoma (4 papers, 2014 to 2025). The most malignant astrocytic tumor (WHO grade IV). "An IHC analysis of PAX5 expression in the brain tumours cohort identified seven PAX5-positive tumours, all glioblastomas." (PMID 24602166, 2014).
liver cancer (4 papers, 2017 to 2026). An epithelial or non-epithelial malignant neoplasm that arises from the liver. "Within the regions prioritised by the combined score, we also identified several extremely highly conserved regions that are recurrently mutated in the LIRI-JP cohort (liver cancer), including non-coding regions of the genes BCL11A, BCL6, and PAX5." (PMID 28056774, 2017).
medulloblastoma (4 papers, 2004 to 2022). A malignant, invasive embryonal neoplasm arising from the cerebellum. "Similarly, elevated PAX5 expression has been associated with pediatric brain tumors (medulloblastomas), where PAX5 expression positively correlates with cell proliferation and inversely with neuronal differentiation in desmoplastic medulloblastoma." (PMID 36077495, 2022). "Dysregulated expression of PAX5 in undifferentiated medulloblastoma cells has further established PAX5 in tumor cell proliferation." (PMID 34012965, 2021).
melanoma (4 papers, 2017 to 2024). A malignant, usually aggressive tumor composed of atypical, neoplastic melanocytes. "We found that PAX5 gene was an efficient marker to measure the effects of methylation inhibitors for in vitro systems for malignant melanoma tissue." (PMID 30792990, 2019). "In our study, PAX5 gene was found methylated in all patients with malignant melanoma for primary tumor tissue and 2D/3D tissue culture systems." (PMID 30792990, 2019). "In the future, we are planning to use PAX5 gene as a biomarker for in vitro 2D/3D culture systems to examine the role of PAX5 gene and/or other genes in the pathogenesis and biologic pathways of malignant melanoma in larger patient groups." (PMID 30792990, 2019). "Our results show that PAX5 gene is an efficient marker to measure the effects of methylation inhibitors such as 5-azacytidine and 5-azadeoxycytidine at in vitro systems for malignant melanoma because the methylation levels are all the same in primary tissue and culture systems." (PMID 30792990, 2019). "Therefore, PAX5 gene was concluded to be the most appropriate gene that could be used to measure the effects of methylation inhibitors in in vitro models for malignant melanoma." (PMID 30792990, 2019).
non-Hodgkin lymphoma (4 papers, 2018 to 2024). Distinct from Hodgkin lymphoma both morphologically and biologically, non-Hodgkin lymphoma (NHL) is characterized by the absence of Reed-Sternberg cells, can occur at any age, and usually presents as a localized or generalized lymphadenopathy associated with fever and weight loss. "In non-Hodgkin lymphoma, a translocation juxtaposing the complete coding region PAX5 with IGH is often observed, representing the aberrant upregulation of PAX5 expression." (PMID 38473380, 2024).
plasmacytoma (4 papers, 2009 to 2018). Plasmacytoma is a localized mass of neoplastic monoclonal plasma cells that represents approximately 5% of all plasma cell neoplasms. "This specific molecular aberration also explains the PAX5 expression detected in the plasmacytoma." (PMID 24715915, 2014). "Our data showed that 3′RR is insensitive to a PAX5A or PAX5B regulation in the S194 plasmacytoma cell line, in agreement to the observation that an hs1,2-dependent transgene is not inhibited whereas Pax5 expression is still detected in activated B cells." (PMID 30214688, 2018). "DNase I footprinting using nuclei of the Pax5-expressing M12 B cell lymphoma cell line shows a definitive protection at the putative Pax5-binding site in comparison to S194 plasmacytoma cells which do not express Pax5." (PMID 24904588, 2014). "The tumor cells were lambda light chain restricted and positive for CD45, weakly positive for CD79a and negative for CD20, CD30, CD10, CD5, BCl-2, Bcl-6, Pax5 and S100, and consistent with anaplastic plasmacytoma." (PMID 19495405, 2009).